RN7SKP48 (RN7SK pseudogene 48)
Gene: Miscellaneous RNA gene on chromosome 4 (85,100,496 to 85,100,823, forward strand). Ensembl gene ENSG00000201901.
Homologues: Orthologues: chimpanzee 7SK (98% identical). Paralogues in human: 7SK (89% identical), RN7SKP185 (84% identical), RN7SKP227 (84% identical), RN7SKP187 (83% identical), RN7SKP174 (83% identical), RN7SKP118 (82% identical), RN7SKP292 (80% identical), RN7SKP55 (80% identical), RN7SKP76 (79% identical), RN7SKP178 (79% identical), RN7SKP62 (79% identical), RN7SKP104 (76% identical), and 284 more.
Diseases named in the same sentence as RN7SKP48 in open-access papers:
RN7SKP48 is named in the same sentence as 1 disease in open-access papers, as found by Europe PMC text mining. Sharing a sentence is not in itself a finding about the gene and the disease.
RN7SKP48 shares sentences with these, for which no sentence is quoted: cancer (1 paper).